ADGRF4 (adhesion G protein-coupled receptor F4)
Description:
Orphan receptor.
Synonyms: GPR115; PGR18; FLJ38076
Tractability: Antibody: UniProt predicts a signal peptide or a membrane-spanning region. PROTAC: ubiquitination databases record sites on it.
Target class: Family B G protein-coupled receptor; Membrane receptor
Gene: Protein-coding gene on chromosome 6 (47,685,864 to 47,722,021, forward strand). Ensembl gene ENSG00000153294.
Subcellular location: Membrane
Subcellular location (Human Protein Atlas): Mitochondria
Gene Ontology:
Molecular function: protein binding; G protein-coupled receptor activity; transmembrane signaling receptor activity
Biological process: adenylate cyclase-activating G protein-coupled receptor signaling pathway; G protein-coupled receptor signaling pathway; cell surface receptor signaling pathway
Cellular component: membrane; plasma membrane
Genetic constraint (gnomAD): Loss-of-function variants: 45 observed, 42.42 expected, observed/expected ratio (o/e) 1.06, 90% interval 0.83 to 1.36. The upper end of that interval is the gene's LOEUF score, 1.36, which puts it in group 5 of 6, group 1 being the genes least tolerant of losing a copy. Missense variants: 770 observed, 728.43 expected, observed/expected ratio (o/e) 1.06, 90% interval 1 to 1.12. Synonymous variants: 260 observed, 256.42 expected, observed/expected ratio (o/e) 1.01, 90% interval 0.92 to 1.12.
Homologues: Orthologues: chimpanzee ADGRF4 (97% identical), macaque ADGRF4 (91% identical), dog ADGRF4 (84% identical), rabbit ADGRF4 (80% identical), pig ADGRF4 (80% identical), guinea pig ADGRF4 (75% identical), rat Adgrf4 (68% identical), mouse Adgrf4 (67% identical). Paralogues in human: ADGRF1 (34% identical), ADGRF5 (33% identical), ADGRF3 (25% identical), ADGRG7 (19% identical), ADGRB1 (19% identical), ADGRB2 (19% identical), ADGRG6 (19% identical), ADGRL3 (18% identical), ADGRD2 (18% identical), ADGRB3 (17% identical), ADGRL2 (17% identical), ADGRD1 (17% identical), and 30 more.
Diseases named in the same sentence as ADGRF4 in open-access papers:
ADGRF4 is named in the same sentence as 16 diseases in open-access papers, as found by Europe PMC text mining. Sharing a sentence is not in itself a finding about the gene and the disease. The quoted sentences say what the papers report.
esophageal cancer (1 paper, 2024). A primary or metastatic malignant neoplasm involving the esophagus. "The positively correlated genes (SLUT2B1, PPL, KLK6, CRYBG2, SCEL, ADGRF4 and KLK8) were more frequently expressed in esophageal cancer than normal tissue (p < .05)." (PMID 38241178, 2024).
inflammatory skin disease (1 paper, 2025). Inflammatory skin disorders covers a broad category that includes many conditions ranging in severity, from mild itching to grave medical health complications These disorders are common in people of all ages and races. "Adhesion G protein-coupled receptor F4 (ADGRF4) has been reported to be involved in the development of inflammatory skin diseases, including psoriasis." (PMID 40756258, 2025).
psoriasis (1 paper, 2025). An autoimmune condition characterized by red, well-delineated plaques with silvery scales that are usually on the extensor surfaces and scalp. "The specific miRNAs related to ADGRF4, KRT1, HELLS, and UHRF1 in psoriasis have not been reported in the literature." (PMID 40756258, 2025).
tumor (4 papers, 2019 to 2025). "The highest expressed GPCRs in PDAC tumors (as an example, this finding is generalizable to other tumor types) are generally overexpressed compared to normal tissue and include orphan receptors (e.g., GPRC5A and ADGRF4/GPR115) and GPCRs with known agonists (e.g., GPR68)." (PMID 31765370, 2019).
ADGRF4 also shares sentences with these, for which no sentence is quoted: breast carcinoma (2 papers); cancer (2); lung adenocarcinoma (2); lung squamous cell carcinoma (2); colon cancer (1); congenital heart defects (1); endometriosis (1); glioma (1); lung carcinoma (1); lymph node metastasis (1); neurodevelopmental disorder (1); skin cancer (1).